PLK4 (polo like kinase 4)
Diseases named in the same sentence as PLK4 in open-access papers (continued):
Sharing a sentence is not in itself a finding about the gene and the disease.
skin tumor (4 papers, 2022 to 2025). "PLK4 overexpression has also been linked with damaging effects of ultraviolet (UV) radiation, which is a major risk factor for skin cancer." (PMID 40940791, 2025). "These pathways have been implicated in PLK4 across multiple cancers; however, their association with PLK4 in skin cancer remains unsubstantiated." (PMID 40940791, 2025). "PLK4 is overexpressed in skin cancer and is associated with centrosome amplification, chromosomal instability, uncontrolled tumor growth, and poor overall survival." (PMID 40940791, 2025). "The subsequent section discusses the current understanding of PLK4′s function in skin-related diseases and skin cancer." (PMID 40940791, 2025). "Although current research linking PLK4 to skin cancer is still in its early stages, preliminary findings are encouraging." (PMID 40940791, 2025). "While these pathways are separately recognized in skin cancer, skin-specific mechanistic studies are needed to establish their specific link to PLK4 within this context." (PMID 40940791, 2025). "Since ATR seems to exhibit dual roles in different skin cancers, it is imperative to delineate the exact interaction between PLK4 and ATR/CHEK1 pathways." (PMID 40940791, 2025). "These insights open avenues for therapeutic intervention targeting PLK4 in both malignant and benign hyperproliferative skin disorders and skin cancer." (PMID 40940791, 2025). "So far, most studies on skin or skin cancer have discussed the influence of PLK4 dysregulation in relation to disrupted centriole biogenesis and centrosome amplification." (PMID 40940791, 2025). "While the role of PLK4 has been widely explored in some solid tumors its contribution to the pathogenesis of skin cancer remains comparatively understudied." (PMID 40940791, 2025). "Building upon this foundation, we provide perspectives on the potential mechanistic contributions of PLK4 in skin cancer development based on the evidence and insights gained from its role in other malignancies." (PMID 40940791, 2025). "They suggest that PLK4 could serve as a viable therapeutic target either as a standalone treatment or as part of a combinatorial approach to combat skin cancer more effectively." (PMID 40940791, 2025). "It is possible that the effect of PLK4 on NF-κB in skin cancer may be pro-proliferative, pro-inflammatory, or both." (PMID 40940791, 2025). "Therefore, investigating how PLK4 synergizes with PI3K/AKT/mTOR axis signaling to accelerate skin cancer progression warrants future studies." (PMID 40940791, 2025). "However, since skin cancers are immunologically hot, it requires in-depth investigation on how modulation of PLK4 will affect STING-mediated immune response and antitumor immunity in skin cancer." (PMID 40940791, 2025). "The role of PLK4 in skin cancers is beginning to be investigated." (PMID 41488365, 2025). "The following section provides a perspective on the potential mechanism of PLK4 in skin cancer, drawing on evidence of its regulation in other cancers and thereby highlighting the need for further research to elucidate specific functions of PLK4 in skin cancer development." (PMID 40940791, 2025). "This requires a comprehensive analysis to define the precise relationship between PLK4 and UV exposure in skin cancer, with careful consideration given to extrapolating findings from fibroblasts to keratinocytes or melanocytes, which are directly implicated in skin carcinogenesis." (PMID 40940791, 2025). "Collectively, PLK4 appears to play a pivotal role in the pathogenesis of skin cancer." (PMID 40940791, 2025). "In this review, we provide a comprehensive overview of the known functions of PLK4 in skin cancer." (PMID 40940791, 2025).
skin tumor (continued). "Additionally that UV affects the ATR/CHEK1 pathway, it would be interesting to study UV-mediated dysregulation of PLK4/ATR/CHEK1 axis in skin cancer models." (PMID 40940791, 2025). "Hence, detailed preclinical investigations are warranted to establish the upstream as well as downstream mechanisms of PLK4 in skin cancer." (PMID 40940791, 2025). "Notably, PLK4 is frequently overexpressed in several cancers, including skin cancer, and its precise role in skin cancer is an area of current investigation." (PMID 40940791, 2025). "Thus, it is speculated that PLK4 inhibition possibly leads to Wnt/β-catenin pathway inactivation, reducing proliferation and tumor growth in skin cancer." (PMID 40940791, 2025). "Analogously, in mice with K14-CRE-driven constitutive overexpression of PLK4 in epidermal cells, DMBA/TPA treatment did not cause increased skin tumor formation and PLK4 -overexpressing mice even exhibited a trend toward lower overall skin tumor volume per animal." (PMID 39466849, 2024). "PLK4 and the PI3K/AKT signaling pathway intersect at several critical nodes in skin cancer biology, though a direct relationship between these important pathways is not known." (PMID 40940791, 2025). "Selective PLK4 inhibitors such as CFI-495004 and RP-1664 have shown promise in clinical trials, although their effectiveness in skin cancer treatment remains to be fully validated." (PMID 40940791, 2025). "Thus, there is a possibility of an interaction between PLK4 and Hippo/YAP pathway components, or PLK4-mediated constant centrosome amplification works synergistically with the dysregulation of Hippo/YAP signaling allowing oncogenic activity of YAP in skin cancer." (PMID 40940791, 2025).
anaplastic thyroid cancer (3 papers, 2023 to 2025). "Inhibition of PLK4 by centrinone also exhibits synergistic anticancer effects with sorafenib in anaplastic thyroid carcinoma." (PMID 41092110, 2025). "The anti-tumor effect of polo-like kinase 4 (PLK4) inhibitor has been explored in several solid carcinomas, while its application in anaplastic thyroid cancer (ATC) remains scarce." (PMID 37351847, 2023).
brain tumors (3 papers, 2017 to 2019). "We previously reported the overexpression of the polo-like kinase 4 (PLK4) in embryonal brain tumors." (PMID 30400339, 2018). "To test our hypothesis, we examined PLK4 expression in NB samples of the CNS as compared to other embryonal brain tumors (ATRT and MB) and low grade gliomas (LGG), which are the most common form of primary CNS tumors." (PMID 30400339, 2018). "We established that PLK4 is overexpressed in embryonal brain tumors such as ATRT and MB." (PMID 30400339, 2018). "PLK4 is an S/T-PK, and we are addressing brain tumors in our studies." (PMID 29340047, 2017). "Further, we suggest that the next generation of brain tumor focused PLK4 inhibitors could be promising agents for use in combination therapies for the treatment of RT and MB." (PMID 29340047, 2017). "Here, we hypothesize that, as in other CNS embryonal brain tumors, CNS-NB overexpress PLK4." (PMID 30400339, 2018). "Our preliminary findings suggested that targeting PLK4 with small-molecule inhibitors may represent a novel strategy to treat EBT and possibly other tumors of the brain." (PMID 31035676, 2019). "In each individual experiment using individual housekeeping genes, CNS-NB samples showed significantly elevated PLK4 expression levels when compared to non-embryonal brain tumors (LGG) (GAPDH p = 0.0016; HPRT1 p < 0.0001; HMBS p = 0.0116)." (PMID 30400339, 2018). "The relative PLK4 expression levels of the NB samples were found to be significantly higher than the non-embryonal brain tumors (p-value < 0.0001 in both our samples and in public databases)." (PMID 30400339, 2018). "Therefore, the finding that a prototype PLK4 inhibitor drug candidate, CFI-400945, is effective in a brain tumor model is a significant finding in itself." (PMID 29340047, 2017). "We evaluated the PLK4 expression by quantitative real-time PCR (qRT-PCR) on the CNS-NB samples and compared the relative expression levels among other embryonal and non-embryonal brain tumors." (PMID 30400339, 2018).
cervical cancer (3 papers, 2021 to 2025). A primary or metastatic malignant neoplasm involving the cervix. "Further investigations demonstrated that the HPV-16 E7 increased the expression of Plk4 by impairing the repression effect of DREAM on the Plk4 promoter in human cervical cancer cell lines." (PMID 33777739, 2021). "This leads to PLK4-mediated centrosome amplification and proliferation of cervical cancer." (PMID 41488365, 2025). "A study showed that PLK4 transcription is regulated by the human papillomavirus (HPV) E7 protein through disrupting the DREAM-CDE/CHR pathway in HPV-infected cervical cancer samples, indicating the potency of PLK4 as a biomarker for HPV-infected cervical cancer." (PMID 38326803, 2024). "In short, PLK4 may have a role in the progression of breast, uterine, and cervical cancer, whose mechanism is not established yet." (PMID 41488365, 2025).
embryonal tumors (3 papers, 2017 to 2019). "Based on the results, we conclude that this PLK4 inhibitor can increase the susceptibility of embryonal cancer cells to DNA-damaging agents due to its role in the initiation and maintenance of polyploidy." (PMID 29340047, 2017). "We previously demonstrated overexpression of PLK4 in embryonal tumors including RT, pediatric MB, and CNS-NB, for which only highly toxic and poorly effective treatments are available." (PMID 31035676, 2019). "Our previous findings together with the findings of the present study highlight the prevalence of PLK4 overexpression in embryonal tumors and suggest the potential of PLK4 as a new target for therapeutic intervention." (PMID 30400339, 2018). "Here, we expand upon our previous work that detected PLK4 overexpression in pediatric embryonal tumors to include CNS-NB." (PMID 30400339, 2018). "We previously demonstrated upregulation of PLK4 in RT and detected this overexpression also in other embryonal tumors of the brain including pediatric MB." (PMID 29340047, 2017). "In this regard, we previously demonstrated that RT cell proliferation is dependent on PLK4 and suggested that PLK4 is a candidate target for the treatment of RT and possibly other embryonal tumors." (PMID 29340047, 2017). "As we previously reported, inhibiting PLK4 in embryonal tumors led to decreased tumor cell proliferation, survival, invasion and migration in vitro and tumor growth in vivo, and therefore PLK4 may be a potential new therapeutic approach to CNS-NB." (PMID 30400339, 2018). "We further illustrate the mechanism of action of the PLK4 inhibitor in these embryonal tumors." (PMID 29340047, 2017). "Our findings indicate that targeting PLK4 with optimized small-molecule inhibitors may hold a novel strategy for the treatment of embryonal tumors, including those of the CNS." (PMID 29340047, 2017).
Infertility (3 papers, 2022 to 2024). "Furthermore, the defects during spermiogenesis are likely the primary cause of reduced epididymal sperm counts and infertility observed for the Plk4 cKO male mice." (PMID 38943004, 2024). "Importantly, PLK4 has been linked with cases of human infertility." (PMID 38943004, 2024). "One patient, carrier of a heterozygous deletion in the Ser/Thr kinase domain of PLK4, presented with infertility due to Sertoli cell-only syndrome, similar to mice heterozygous for a Plk4 -null mutation." (PMID 38764035, 2024). "Characterization of PLK4 in the context of spermatogenesis, as well as the identification of the ncMTOC are key findings that can help contribute to developing better treatment for patients experiencing these kinds of subfertility or infertility issues." (PMID 38943004, 2024). "As we observed round spermatids in Plk4 and Sas4 cKO mice, procedures such as round spermatid injection (ROSI) or other reproductive interventions could be used to overcome infertility caused by centriole biogenesis defects." (PMID 38943004, 2024).
leukemia (3 papers, 2018 to 2025). A malignant (clonal) hematologic disorder, involving hematopoietic stem cells and characterized by the presence of primitive or atypical myeloid or lymphoid cells in the bone marrow and the blood. "PLK4 inhibitor mediated senescence and upregulated cytokine response was ameliorated when leukemia cells were treated with cGAS or STING inhibitor." (PMID 40940791, 2025). "PLK1 and PLK4 expression levels are higher in leukemia cells than in non-tumorous cells and have promise as being new targets for cancer therapy." (PMID 35256538, 2022).
medulloblastoma (3 papers, 2017 to 2025). A malignant, invasive embryonal neoplasm arising from the cerebellum. "PLK4 is upregulated in pediatric medulloblastoma, rhabdoid tumors and other embryonal tumors of the brain." (PMID 41092110, 2025).
renal cell carcinoma (3 papers, 2023 to 2025). "Another study indicated that increased PLK4 mRNA expression is associated with tumor size ≥ 7 cm and high tumor node metastasis (TNM) stage in renal cell carcinoma." (PMID 38326803, 2024). "This suggested that high PLK4 expression in renal cell carcinoma may be regulated by PLK4 methylation levels." (PMID 41488365, 2025). "According to CTRP drug sensitivity analysis, high level of CBX2, BLNK, PLK4, STIL and BIRC5 were associated with increased sensitivity to inhibitors of VEGF and MET pathways, which happened to be two crucial driver pathways of renal cell carcinoma." (PMID 37917664, 2023).
Seckel syndrome (3 papers, 2021 to 2025). A rare autosomal recessive inherited syndrome caused by mutations in the ATR gene, RBBP8 gene, CENPJ gene, CEP152 gene, CEP63 gene, NIN gene, DNA2 gene, or TRAIP gene. "Inherited mutations in PLK4 have been implicated in forms of microcephalic primordial dwarfism such as Seckel syndrome, microcephaly, growth failure and chorioretinopathy." (PMID 41092110, 2025). "Moreover, mutation of Polo-like kinase 4 (Plk4) gene and resultant centrosome dysfunction and cilium defect have been identified as causes in the pathophysiology of autosomal recessive developmental disorders, Seckel syndrome (SCKL)." (PMID 35047005, 2021). "Unlike individuals with PCNT-related phenotype, individuals carrying PLK4 mutations did not exhibit proportionate dwarfism (height and OFC not reduced equally) as expected in Seckel syndrome." (PMID 37443841, 2023).
thyroid cancer (3 papers, 2022 to 2025). "Similarly, centrinone, a PLK4 small molecule inhibitor, has been shown to inactivate Wnt/β-catenin signaling along with decreased cell viability and cell cycle arrest in thyroid cancer cells." (PMID 40940791, 2025).
basal cell carcinoma (2 papers, 2022 to 2025). A carcinoma involving the basal cells. "PLK4 is significantly overexpressed in cutaneous squamous cell and basal cell carcinoma cells and tissues; knockdown of PLK4 in the cutaneous squamous cell carcinoma cells results in growth inhibition in vitro and reduction of tumorigenesis in a mouse xenograft model." (PMID 41092110, 2025). "Polo-like kinase 4 (PLK4) is a master regulator of centriole replication, and its overexpression has been identified in in vitro and ex vivo studies of basal cell carcinoma (BCC) and SCC of the skin." (PMID 36009523, 2022).
Cirrhosis (2 papers, 2011 to 2012). A chronic disorder of the liver in which liver tissue becomes scarred and is partially replaced by regenerative nodules and fibrotic tissue resulting in loss of liver function. "There were no statistical connections between PLK4 expression and the rest clinicopathological parameters, such as age, gender, HBsAg, cirrhosis, differentiation and vascular invasion (P>0.05)." (PMID 22829937, 2012).
clear cell renal cell carcinoma (2 papers, 2022 to 2025). "In clear cell renal cell carcinoma, PLK4 mRNA expression levels are significantly higher compared with paracancerous tissues and are associated with poor prognosis in patients, as well as are closely related to immunosuppressive phenotypes." (PMID 41092110, 2025). "The results of the Kaplan-Meier plotter database survival analysis showed that high levels of PLK4 expression were an unfavorable prognostic factor for survival in patients with renal clear cell carcinoma." (PMID 36176741, 2022). "However, the role of PLK4 in clear cell renal cell carcinoma (ccRCC) is still unclear." (PMID 36176741, 2022). "According to the results of the GEPIA2 database, PLK4 was not significantly differentially expressed in different pathological stages of renal clear cell carcinoma in stages I, II, and III and slightly higher in stage IV." (PMID 36176741, 2022). "To further determine the expression of PLK4 in ccRCC, we separately analyzed the gene expression levels of PLK4 between renal clear cell carcinoma and its paraneoplastic tissues using the UALCAN database, and PLK4 was highly expressed in renal clear cell carcinoma tissues compared to normal tissues." (PMID 36176741, 2022).
colorectal tumor (2 papers, 2012 to 2024). "Increased RNA expression of PLK4 was found in colorectal tumor samples compared to normal tissues as evidenced in two independent clinical datasets." (PMID 38951519, 2024). "Reduced expression of PLK4 was reported to connect with age in colorectal tumor." (PMID 22829937, 2012).
diffuse large B-cell lymphoma (2 papers, 2021 to 2025). "PLK4 overexpression is observed in diffuse large B-cell lymphoma (DLBCL) and is associated with poor survival in patients receiving cyclophosphamide, doxorubicin (hydroxydaunorubicin), vincristine (oncovin), and prednisone (CHOP)-based treatment." (PMID 41092110, 2025). "Nevertheless, the role of PLK4 in diffuse large B-cell lymphoma (DLBCL) is still undefined." (PMID 34162828, 2021).
Ewing sarcoma (2 papers, 2020 to 2025). A small round cell tumor that lacks morphologic, immunohistochemical, and electron microscopic evidence of neuroectodermal differentiation. "Our findings show that PLK4 inhibitors were effective against Ewing’s sarcoma cells in vitro and thus provide a rationale for their evaluation in vivo." (PMID 32770382, 2020).
HIV-1 infection (2 papers, 2023 to 2024). The type species of lentivirus and the etiologic agent of acquired immunodeficiency syndrome (AIDS). "We propose that the Vpr•VprBP•Plk4 complex serves as a molecular link that connects HIV-1 infection to oncogenesis and that inhibiting the Vpr C-terminal motif may reduce the occurrence of HIV-1-associated cancers." (PMID 37645926, 2023). "Therefore, since Plk4 is a master regulator of centrosome duplication, we investigated whether its function is deregulated under HIV-1 infection." (PMID 38443376, 2024). "Furthermore, since Plk4 is a master regulator of centrosome duplication, its function could have been deregulated under HIV-1 infection." (PMID 37645926, 2023).